RN7SL605P (RNA, 7SL, cytoplasmic 605, pseudogene)
Gene: Miscellaneous RNA gene on chromosome 11 (57,528,085 to 57,528,365, reverse strand). Ensembl gene ENSG00000265566.
Homologues: Paralogues in human: RN7SL455P (70% identical), Metazoa_SRP (66% identical), Metazoa_SRP (65% identical), Metazoa_SRP (64% identical), Metazoa_SRP (63% identical), RN7SL531P (63% identical), Metazoa_SRP (62% identical), Metazoa_SRP (61% identical), Metazoa_SRP (60% identical), RN7SL73P (60% identical), Metazoa_SRP (59% identical), Metazoa_SRP (58% identical), and 703 more.